ENO1 (enolase 1)
Diseases named in the same sentence as ENO1 in open-access papers (continued):
Sharing a sentence is not in itself a finding about the gene and the disease.
asthma (3 papers, 2012 to 2022). "Genes that the identified CpGs were mapped to, e.g., AKAP1 and ENO1, have been shown to be associated with the risk of asthma." (PMID 35207690, 2022). "The connection of gene ENO1 with asthma acquisition shown in our study is consistent with its differentiation between severe and mild-to-moderate asthma." (PMID 35207690, 2022).
Autoimmunity (3 papers, 2013 to 2023). The occurrence of an immune reaction against the organism's own cells or tissues. "ENO1 is normally expressed in the cytosol and displayed on the cell surface mainly during pathological conditions such as inflammation, autoimmunity, and malignancy." (PMID 23894455, 2013).
brain tumors (3 papers, 2010 to 2024). "In a subpopulationof brain tumors, due to the mutation or deletion of glycolysis-relatedgenes such as ENO1,49,53 the tumors are glycolysis-deficient,thus heavily dependent on OXPHOS." (PMID 38559310, 2024). "The loss of enolase 1 (ENO1) was found to be predictive of sensitivity to IACS-010759 in some brain tumour cell lines (D423, Gli56)." (PMID 33092283, 2020).
Cognitive impairment (3 papers, 2017 to 2021). Abnormal cognition is characterized by deficits in thinking, reasoning, or remembering. "Transcripts predictive of cognitive performance under high stress included genes that are associated with a high occurrence of Alzheimer's and cognitive impairments (e.g., Ncl, Eno1, Scn9a, Slc19a3, Ncstn, Fos, Eif4h, Copa, etc.)." (PMID 28912681, 2017). "A previous study using Redux proteomics reported dysregulation of ENO1 in cases of mild cognitive impairment (MCI) and is associated with modified hippocampus proteins and malfunction, indicating that inactivation of ENO1 leads to the development of AD from MCI." (PMID 34243818, 2021).
cutaneous melanoma (3 papers, 2022 to 2025). A primary melanoma arising from atypical melanocytes in the skin. "In the present study, we aimed to determine the role of ENO1 in skin cutaneous melanoma (SKCM) and the potential underlying mechanism." (PMID 35925486, 2022). "Alpha-enolase (ENO1) undergoes accentuated overexpression in several solid cancers, but little is known about its status in cutaneous melanoma." (PMID 35204345, 2022). "Nodular melanomas, a histologic subtype of cutaneous melanoma with a worse outcome, revealed the highest level of ENO1 expression in comparison to superficial spreading and acral lentiginous melanomas (p < 0.001)." (PMID 35204345, 2022). "In the future study, we will test the influence of alternatively spliced nuclear isoform of the ENO1–MBP−1 (a transcriptional repressor of multiple protooncogenes) on cutaneous melanoma cells proliferation and invasion." (PMID 35204345, 2022). "Elevated expression of ENO1 in tumor cells in a cohort of 112 cutaneous melanoma patients correlated with unfavorable prognosticators such as high Breslow thickness, Clark level, increased mitotic activity, and presence of ulceration." (PMID 35204345, 2022). "ENO1 expression was evaluated by immunohistochemistry performed on tissue microarrays generated from 112 primary cutaneous melanomas (archival formalin-fixed, paraffin-embedded specimens)." (PMID 35204345, 2022). "The expression of ENO1 also positively correlated with a greater thickness of the neoplastic infiltrate and a worse long-term prognosis for patients with cutaneous melanoma." (PMID 35204345, 2022). "Previously, it was found that in five human skin melanoma cell lines (A375, MeWo, MEL-HO, Colo−800, and Colo−853), the RNA expression levels for ENO1 were upregulated 8−16 fold." (PMID 35204345, 2022).
Diabetic Nephropathy (3 papers, 2021 to 2025). "WTAP-mediated m6A modification of glycolytic enzyme ENO1 promotes the progression of diabetic nephropathy." (PMID 39945887, 2025).
lung squamous cell cancer (3 papers, 2010 to 2023). "The purpose of this study is to investigate the significance of alpha-enolase (ENO1) expression in squamous cell carcinoma of the lung (LUSC), its prognostic value, and prospective molecular mechanism." (PMID 34504528, 2021). "The ENO1 protein levels in the tumor tissues and corresponding normal tissues from 16 cases of lung squamous cell carcinoma were analyzed by Western blot." (PMID 21159241, 2010). "For 87.5% (14/16) of the patients with lung squamous cell carcinoma, the ENO1 protein level in the tumor tissues was higher than that in the corresponding normal lung tissues." (PMID 21159241, 2010). "Furthermore, the ENO1 protein level was significantly higher in the plasma of patients with lung adenocarcinoma than that of patients with lung squamous cell carcinoma." (PMID 21159241, 2010). "CAT, ENO1, NQO1, P4HB, and PDIA6 were unique to LUAD, while CAV1, GAPDH, GPX2, GPX3, and PDIA4 exhibited consistent trends in differential expression in both LUAD and lung squamous cell cancer, significant prognostic survival prediction (p<0.05), and excellent classification effectiveness." (PMID 37955007, 2023).
metastatic cancer (3 papers, 2013 to 2022). A carcinoma which has spread from the original site of growth to another anatomic site. "The enolase-1 isozyme (ENO1) is another glycolytic enzyme that is increased in metastatic cancer cells." (PMID 36430377, 2022). "ENO1 has a multifunctional role in promoting the invasion of metastatic cancer, depending on its localization in the cytoplasm." (PMID 31798634, 2019). "In addition, ENO1 is more highly expressed in metastatic cancer cells compared with primary cancer cells, suggesting an oncogenic role of ENO1." (PMID 23504277, 2013).
non-Hodgkin lymphoma (3 papers, 2017 to 2019). Distinct from Hodgkin lymphoma both morphologically and biologically, non-Hodgkin lymphoma (NHL) is characterized by the absence of Reed-Sternberg cells, can occur at any age, and usually presents as a localized or generalized lymphadenopathy associated with fever and weight loss. "Highly expressed ENO1 is correlated with non-Hodgkin lymphoma and glioma progression." (PMID 29497031, 2018).
oral cancer (3 papers, 2020 to 2024). "NEDD4L inhibits oral cancer proliferation by inducing ENO1 ubiquitination and degradation." (PMID 38520027, 2024).
osteoarthritis (3 papers, 2022 to 2023). A noninflammatory degenerative joint disease occurring chiefly in older persons, characterized by degeneration of the articular cartilage, hypertrophy of bone at the margins and changes in the synovial membrane. "It was also found that ENO1 could promote osteoarthritis progression through interacting with Circular RNA circNFKB1 and sustaining NF-κB signaling." (PMID 37291167, 2023).
Parkinson disease (3 papers, 2016 to 2022). A progressive degenerative disorder of the central nervous system characterized by loss of dopamine producing neurons in the substantia nigra and the presence of Lewy bodies in the substantia nigra and locus coeruleus. "In particular, downregulation of ENO1 in striatum of PQ-treated mice mimicking Parkinson’s disease has been previously reported." (PMID 27111068, 2016). "In addition, KEGG analysis demonstrated that ENO1 co-expressed genes were principally involved in amyotrophic lateral sclerosis, pathways of neurodegeneration-multiple disease and parkinson disease." (PMID 35836227, 2022).
allergic reactions (2 papers, 2005 to 2019). "The multifunctional enolase enzyme encoded by ENO1 is involved in glycolysis; it plays an important role in such biological processes as growth control, tolerance to hypoxia, and allergic reactions." (PMID 30913238, 2019).
astrocytoma (2 papers, 2022 to 2025). "ENO1 has been shown to undergo substantial changes in astrocytoma tissues and is associated with the activation of NF-κB, modulation of E-cadherin expression, and the PI3K/AKT signaling pathway." (PMID 39936033, 2025).
Barrett esophagus (2 papers, 2021 to 2023). Esophageal lesion lined with columnar metaplastic epithelium which is flat or villiform. "ENO1 expression was analyzed by immunohistochemistry in paired tumor and non-tumor tissue samples from 40 EC cases and mucosal biopsies from 45 Barrett's esophagus (BE) cases, plus in plasma from these patients and 25 matched healthy controls." (PMID 33628097, 2021). "Online database showed PPARγ could directly bind to the promoter region of ENO1 promoter and ChIP-seq data in esophageal adenocarcinoma showed prominent binding peaks of PPARγ on ENO1 promoter region." (PMID 37024456, 2023).
bladder tumor (2 papers, 2022). "Furthermore, results from GSE13507 revealed that the mRNA level of ENO1 and ENO2 were increased in bladder tumor tissues as compared to normal counterparts." (PMID 35836227, 2022). "Consistently, data from TIMER database manifested that mRNA expression of ENO1, but not ENO2 and ENO3, was upregulated in bladder tumor tissues." (PMID 35836227, 2022).
cardiac hypertrophy (2 papers, 2019 to 2021). "As confirmed by Western blotting examination, T89 significantly reversed the expression pattern of glycolytic enzyme Eno-1 caused by ISO, similar to that in models of pressure overload-induced cardiac hypertrophy." (PMID 34262469, 2021).
Chlamydia infection (2 papers, 2017 to 2018). "This indicates that ENO1 is an essential anti-apoptotic molecule in DCs during chlamydia infection and that IL-10 deficiency that upregulates ENO1 in DCs decreases susceptibility to apoptosis." (PMID 28525970, 2017). "To find out if ENO1 was associated with the immunoregulatory properties of DCs during chlamydia infection we first silenced ENO1 gene in DCs using siRNA lentiviral system to knockdown the gene." (PMID 28525970, 2017). "Previously, Chlamydia infection was shown to increase mitochondrial permeability in parallel with mitochondrial remodeling in Enolase1 (ENO1)-dependent manner in mouse bone marrow-derived DCs." (PMID 30455688, 2018). "To understand the role of ENO1 in DCs during chlamydia infection, we first determined its intracellular location, as this had been shown to play a role to play in its function." (PMID 28525970, 2017). "In summary, we have concluded that ENO1 is important in the functioning of DCs during chlamydia infection." (PMID 28525970, 2017). "In this study, we performed a preliminary study to elucidate a role for ENO1 in the function of DCs during Chlamydia infection." (PMID 28525970, 2017). "The results showed that WT mice that were adoptively transferred with Chlamydia pulsed IL-10−/− and WT DCs were better able to clear their Chlamydia infection compared to mice that were adoptively transferred with Chlamydia pulsed ENO1 knockdown DCs." (PMID 28525970, 2017). "Furthermore, we wanted to show in vivo that ENO1 is important in clearing Chlamydia infection, so we carried out an adoptive transfer experiment." (PMID 28525970, 2017). "We later validated this through Western blotting and confocal microscopy analysis, where we showed that ENO1 expression decreased with time in WT DCs during Chlamydia infection, however, the levels of ENO1 in IL-10−/− DCs remained consistently high all through." (PMID 28525970, 2017). "Interestingly, tumor necrosis factor (TNF)-α, which induces apoptosis of infiltrating inflammatory cells during genital Chlamydia infection was highly expressed in ENO1 knockdown DCs (p ≤ 0.05)." (PMID 28525970, 2017). "In our ongoing study of the function of IL-10−/− DCs during Chlamydia infection, we observed using 2-DIGE proteomics, the differential expression of the protein ENO1, which was up regulated in IL-10−/− DCs compared to WT DCs." (PMID 28525970, 2017).
chronic lymphocytic leukaemia (2 papers, 2016 to 2024). "Circulating anti-ENO1 antibodies have also been detected in blood from chronic lymphocytic leukaemia patients with progressive disease, suggesting a possible predictive role for this biomarker in haematological malignancies." (PMID 38473245, 2024).
chronic myeloid leukaemia (2 papers, 2015 to 2023). "Because haematological cells, both cancer and primary cells, have clear responses to treatment with APIM-peptides, F in KFAGR in ENO1 was mutated in the haploid chronic myeloid leukaemia cell line HAP1." (PMID 36564470, 2023).
Cirrhosis (2 papers, 2020 to 2021). A chronic disorder of the liver in which liver tissue becomes scarred and is partially replaced by regenerative nodules and fibrotic tissue resulting in loss of liver function. "In addition, IHC staining of a tissue microarray containing 2 normal liver tissues, 6 cirrhosis tissues, 17 paired of HCC and non-tumorous tissues and 14 HCC metastasis tissues showed that ENO1 expression was significantly higher in HCC metastasis tissues than in the other tissue types assessed." (PMID 33184263, 2020).
diffuse large B-cell lymphoma (2 papers, 2019 to 2025). "Alpha-enolase (ENO1), the enzyme catalyzing 2-phosphoglycerate conversion to phosphoenolpyruvate, is highly expressed in diffuse large B-cell lymphoma (DLBCL) and correlates with adverse clinical outcomes." (PMID 41208958, 2025).
ductal invasive carcinoma (2 papers, 2024 to 2025). "ENO1 overexpression recruits a range of signalling pathways during disease progression conferring a worse prognosis and can be potentially used as a biomarker of disease progression and therapeutic target, particularly in triple-negative and in ductal invasive carcinoma." (PMID 39483155, 2024).
esophageal squamous cell carcinoma (2 papers, 2021 to 2022). Esophageal squamous cell carcinoma (ESCC) is a type of esophageal carcinoma (EC) that can affect any part of the esophagus, but is usually located in the upper or middle third. "ENO1 was abnormally elevated in cancer-cell cytoplasm in both EC types, in esophageal squamous cell carcinoma and in adenocarcinoma (EAC), increasing significantly with tumor stage progression and the transition from BE to EAC." (PMID 33628097, 2021).
follicular thyroid carcinoma (2 papers, 2016 to 2017). "It was reported that down regulation of Eno-1 weakened invasiveness of the follicular thyroid carcinoma cell lines." (PMID 26918350, 2016).
gastric adenocarcinoma (2 papers, 2017 to 2022). "Similarly, neuron-specific enolase, another enolase subtype homogenous to ENO-1, was higher in sera of gastric adenocarcinoma cases than in those of healthy individuals." (PMID 36295613, 2022). "ENO1 expression in primary gastric adenocarcinoma and non-tumor tissues were evaluated by immunohistochemistry staining." (PMID 28548950, 2017).
HIV-1 infection (2 papers, 2015 to 2020). The type species of lentivirus and the etiologic agent of acquired immunodeficiency syndrome (AIDS). "The results provide and new insights into the function of ENO1 as a moonlighting protein in HIV-1 infection." (PMID 32917235, 2020). "However, when we performed nested Alu-gag PCR analysis, which is generally used for calculation of integrated viral cDNA, we found that ENO1 knockdown increased the integration efficiency, which correlates with an enhanced HIV-1 infection." (PMID 32917235, 2020). "Therefore, in this study, we examined whether GAPDH and ENO1 expression levels were changed by HIV-1 infection." (PMID 32917235, 2020). "As a result, the same amount of ENO1 was detected in the nuclear fraction from noninfected or infected cells, indicating that ENO1 nuclear localization was unaffected by acute HIV-1 infection." (PMID 32917235, 2020). "Our results show decreased levels of Glut-1 and Eno-1 mRNAs in activated cells, principally at 24h post HIV-1 infection suggesting that HIV-1 infection may negatively affects important metabolic processes in the host cells." (PMID 25875202, 2015).
interstitial lung disease (2 papers, 2023 to 2024). A diverse group of lung diseases that affect the lung parenchyma. "Further, ENO1 antibodies have been linked to fibrogenesis in glomerular nephropathy and interstitial lung disease." (PMID 39408890, 2024).
ischemic stroke (2 papers, 2024 to 2025). A stroke disorder caused by obstruction of blood flow to the brain, due to thrombotic (local blood clot formation) or embolic (due to a blood clot or other material traveling from another site) event. "ENO1, known to exacerbate neurological dysfunction when knocked down after ischemic stroke, was of particular interest." (PMID 39467260, 2025). "Among them, KAD1 (adenylate kinase isoenzyme 1) and ENO1 (α‐enolase) were identified and are known to contribute to vascular inflammation and cerebroprotection against ischemic stroke." (PMID 38420847, 2024). "Considering that circFndc3b acts as a scaffold for ENO1 to stabilize Klf2 mRNA, these results suggest that exercise may confer neuroprotection after ischemic stroke via the circFndc3b/ENO1/Klf2 pathway." (PMID 39467260, 2025). "Consequently, exercise‐mediated circFndc3b exerted neuroprotective effects in ischemic stroke by regulating the circFndc3b/ENO1/Klf2 pathway and establishing a positive feedback loop via circFndc3b/ENO1/FUS, making circFndc3b a potential therapeutic target for stroke intervention." (PMID 39467260, 2025).